EAF2 (ELL associated factor 2)
Description:
Acts as a transcriptional transactivator of TCEA1 elongation activity (By similarity). Acts as a transcriptional transactivator of ELL and ELL2 elongation activities. Potent inducer of apoptosis in prostatic and non-prostatic cell lines. Inhibits prostate tumor growth in vivo.
Synonyms: TRAITS; BM040; U19
Tractability: PROTAC: ubiquitination databases record sites on it.
Gene: Protein-coding gene on chromosome 3 (121,835,183 to 121,886,526, forward strand). Ensembl gene ENSG00000145088.
Subcellular location: Nucleus speckle
Pathways (Reactome):
Gene expression (Transcription): Formation of RNA Pol II elongation complex; RNA Polymerase II Pre-transcription Events; RNA Polymerase II Transcription Elongation
Gene Ontology:
Molecular function: protein binding; transcription elongation factor activity
Biological process: positive regulation of transcription by RNA polymerase II; regulation of transcription elongation by RNA polymerase II; transcription elongation by RNA polymerase II
Cellular component: transcription elongation factor complex; nucleoplasm; nuclear speck; super elongation complex
Genetic constraint (gnomAD): Loss-of-function variants: 15 observed, 20.34 expected, observed/expected ratio (o/e) 0.74, 90% interval 0.49 to 1.14. The upper end of that interval is the gene's LOEUF score, 1.14, which puts it in group 4 of 6, group 1 being the genes least tolerant of losing a copy. Missense variants: 236 observed, 261.48 expected, observed/expected ratio (o/e) 0.9, 90% interval 0.81 to 1. Synonymous variants: 83 observed, 86.13 expected, observed/expected ratio (o/e) 0.96, 90% interval 0.81 to 1.16.
Homologues: Orthologues: macaque EAF2 (97% identical), chimpanzee EAF2 (94% identical), dog EAF2 (86% identical), rabbit EAF2 (83% identical), guinea pig EAF2 (81% identical), pig EAF2 (81% identical), mouse Eaf2 (81% identical), rat Eaf2 (71% identical), tropical clawed frog eaf2 (66% identical), zebrafish eaf2 (66% identical), Drosophila melanogaster Eaf (39% identical), Caenorhabditis elegans eaf-1 (27% identical). Paralogues in human: EAF1 (57% identical).
Diseases named in the same sentence as EAF2 in open-access papers:
EAF2 is named in the same sentence as 31 diseases in open-access papers, as found by Europe PMC text mining. Sharing a sentence is not in itself a finding about the gene and the disease. The quoted sentences say what the papers report.
prostate carcinoma (14 papers, 2010 to 2024). A carcinoma that arises from epithelial cells of the prostate gland. "RNA Polymerase II Elongation Factor (ELL)-associated factor 2 (EAF2) is a tumor suppressor frequently down-regulated in human prostate cancer." (PMID 27058417, 2016). "ELL-associated factor 2 (EAF2) is an androgen-responsive tumor suppressor frequently deleted in advanced prostate cancer that functions as a transcription elongation factor of RNA Pol II through interaction with the ELL family proteins." (PMID 24260246, 2013). "ELL-associated factor 2 (EAF2) is a potential tumor suppressor gene that was found to be up-regulated in response to androgens in the rat ventral prostate and in the human prostate cancer cell line LNCaP." (PMID 24260246, 2013). "EAF2 protein down-regulation, allelic loss, promoter hypermethylation and possibly homozygous deletion was identified in ∼80% of advanced prostate cancer specimens examined (Gleason ≥7)." (PMID 24260246, 2013). "Given that EAF2 inactivation and deficiency may lead to prostate cancer, the upregulated expression of EAF2 may be partly responsible for protecting hyperplastic prostate tissues from malignancy." (PMID 39588149, 2024). "Therefore, therapeutic agents targeting STAT3 may be promising for prostate cancer patients exhibiting EAF2 deficiency." (PMID 39588149, 2024). "In addition to prostate cancer, EAF2 is associated with other tumors and malignancies." (PMID 39588149, 2024). "Our findings suggested that EAF2 was involved in the infiltration of CD163-positive macrophages in prostate cancer via MIF." (PMID 38969982, 2024). "Further understanding of EAF2 will provide new opportunities and therapeutic approaches for cancers, especially prostate cancer." (PMID 39588149, 2024). "In this study, we performed immunohistochemical staining on prostate cancer specimens using antibodies against EAF2 and CD163, a marker of M2 macrophages." (PMID 38969982, 2024). "In expression profile of human prostate cancer tissue, the concurrent downregulation of EAF2 and upregulation of VEGF were in accord with the results observed in mice." (PMID 39588149, 2024). "Our study is the first, to the best of our knowledge, to reveal that EAF2 can engage with the TME to facilitate the progression of prostate cancer." (PMID 38969982, 2024). "Based on this, we further analyzed the expression relationship between EAF2 and a variety of immune regulatory genes in prostate cancer, and drew the enrichment map of up-regulated gene set in prostate cancer." (PMID 38969982, 2024). "This study aimed to examine the expression of EAF2 in prostate cancer and its relationship with the recruitment and polarization of TAMs." (PMID 38969982, 2024). "Our study demonstrated that in specimens of human prostate cancer, the expression of EAF2 was notably downregulated, and this decrease was inversely associated with the number of CD163-positive macrophages that infiltrated the cancerous tissue." (PMID 38969982, 2024). "EAF2 is an androgen-responsive tumor suppressor in the prostate, and it interacts with multiple genes via different pathways to influence prostate cancer." (PMID 39588149, 2024). "ELL-associated factor 2 (EAF2), a tumor suppressor that has been identified in the prostate, is often downregulated in prostate cancer." (PMID 38969982, 2024). "EAF2, also referred to as ELL-associated factor 2, has recently been identified as a tumor suppressor in prostate cancer and is frequently downregulated in this disease." (PMID 38969982, 2024). "In summary, our investigation offers novel insights into EAF2 as a potential tumor suppressor in prostate cancer." (PMID 38969982, 2024).
prostate carcinoma (continued). "We first identified differentially expressed genes in prostate cancer patients with different EAF2 expression groups." (PMID 38969982, 2024). "To investigate the potential correlation between EAF2 expression and macrophage recruitment in prostate cancer patients, we conducted immunohistochemistry (IHC) staining against CD163." (PMID 38969982, 2024). "The role of EAF2 in leukemia, prostate cancer, colorectal cancer, glioblastoma, and gastric cancer has been identified." (PMID 39588149, 2024). "According to their patient data, EAF2 and PTEN are downregulated concurrently in >50% of advanced human prostate cancer (Gleason scores of 8–9) specimens, indicating that EAF2 and PTEN co-downregulation represents poor prognosis." (PMID 39588149, 2024). "SIAH2 participated in the regulation of EAF2 polyubiquitin in prostate cancer cells as E3 ligase of EAF2 polyubiquitination." (PMID 32296631, 2020). "For example, EAF2 is a key factor mediating androgen protection of DNA damage via Ku70/Ku80 in prostate cancer cells." (PMID 32077223, 2020). "Knockout of EAF2 gene in mice led to the development of high grade prostatic intraepithelial neoplasia, the putative precursor of prostate cancer." (PMID 27058417, 2016). "Overexpression of EAF2 induced apoptosis in cultured prostate cancer cells as well as in prostate cancer xenograft tumors, and EAF2 knockdown in LNCaP cells enhanced the expression of androgen receptor (AR)-target genes, cell proliferation, and migration." (PMID 27058417, 2016). "Immunostaining revealed EAF2 downregulation in ~80% high Gleason grade human prostate cancer specimens and in all tested prostate cancer cell lines." (PMID 27058417, 2016). "EAF2 has been previously known as a transcriptional elongation factor and a proapoptotic gene lost in prostate cancer." (PMID 26935903, 2016). "We used HEK293 cells to study EAF2 polyubiquitination because the transfection efficiency in HEK293 cells is much higher than in prostate cancer cells." (PMID 27058417, 2016). "Overexpression of EAF2 in prostate cancer cell lines induced apoptosis and inhibited the growth of xenograft tumors." (PMID 24260246, 2013). "Compared to matched benign tissues, EAF2 staining intensity was significantly reduced in prostate cancer tissues while microvessel density was increased." (PMID 24260246, 2013). "EAF2/19 inhibits xenograft prostate tumor growth and is down-regulated in prostate cancer cell lines." (PMID 20161747, 2010). "Our findings suggest that EAF2 may facilitate the accumulation of macrophages within prostate cancer tissue through MIF-mediated mechanisms." (PMID 38969982, 2024). "Our results indicated that the downregulation of EAF2 in prostate cancer may increase the accumulation of macrophages by promoting the production of migration inhibitory factor (MIF)." (PMID 38969982, 2024). "However, in androgen-sensitive human prostate cancer cells, although EAF2 activated the apoptosis process, androgens protected the cells from death." (PMID 39588149, 2024). "Therefore, understanding the close relationship between EAF2 and androgens would result in the exploration of the pathophysiology of prostate cancer and possible treatments." (PMID 39588149, 2024). "EAF2 has been proposed as a prognostic factor in prostate cancer." (PMID 33194730, 2020). "Our results provided new insights into the mechanisms regulating EAF2 protein turnover, which may eventually lead to novel approaches to stabilize EAF2 and subsequently enhance its tumor suppressive activity in prostate cancer." (PMID 27058417, 2016).
prostate carcinoma (continued). "Interestingly, the expression of its binding partner ELL2 is also induced by androgens in prostate cancer cells, suggesting that EAF2 and ELL2 expression are induced coordinately by androgens in the prostate." (PMID 27058417, 2016). "The elevated expression of SIAH2 may not only increase the transcriptional activity of AR, but also potentially reduce EAF2 protein level and its potential tumor suppressive activity, further promoting malignant growth of prostate cancer." (PMID 27058417, 2016). "EAF2 has previously been shown to be down-regulated in human prostate cancer specimens." (PMID 24260246, 2013). "Our findings suggest a previously unknown role for EAF2 as a tumor suppressor in prostate cancer." (PMID 38969982, 2024). "For example, EAF2/U19 may serve as a tumor suppressor in prostate cancer." (PMID 20161747, 2010). "A large-scale clinical study is still needed to determine the effect of EAF2-PTEN interactions on castration resistance and prostate cancer prognosis." (PMID 39588149, 2024). "Epigenetic repression of EAF2-HIF1α by EZH2 has been shown to foster metabolic reprogramming in glioblastoma and to promote aerobic glycolysis by upregulating HK2 in prostate cancer." (PMID 35888776, 2022). "The presence of proteasome inhibitor, MG132, significantly blocked EAF2 protein decay in the presence of CHX in both LNCaP and C4-2 prostate cancer cell lines." (PMID 27058417, 2016). "When EAF2 knockout was combined with PTEN heterozygous deletion, the double knockout mice developed prostate cancer." (PMID 27058417, 2016). "In order to further examine the potential correlation of EAF2 and ADAMTS1 in human prostate cancer, mRNA levels of EAF2 and ADAMTS1 were analyzed in laser capture microdissected human prostate tissue specimens." (PMID 24260246, 2013). "EAF2 and ADAMTS1 expression were also decreased significantly in human prostate cancer compared to normal adjacent tissues." (PMID 24260246, 2013). "Both EAF2 and ADAMTS1 mRNA expression levels were significantly reduced in prostate cancer tissues compared to normal adjacent tissue." (PMID 24260246, 2013). "This negative correlation between EAF2 expression and macrophage infiltration in prostate cancer tissues was observed." (PMID 38969982, 2024). "Therefore, it is hypothesized that EAF2 may not only have a direct effect on tumor cells but also an indirect effect through the recruitment of macrophages mediated by MIF, promoting prostate cancer progression." (PMID 38969982, 2024).
B-cell lymphoma (4 papers, 2011 to 2024). "Recently, Eaf2 knockout in a mouse model was associated with neoplasia of the lung, liver and prostate as well as B-cell lymphoma." (PMID 21483694, 2011). "However, the mechanism underlying the relationship between EAF2, lung adenocarcinoma, and B-cell lymphoma remains to be explored." (PMID 39588149, 2024). "EAF2-null and -heterozygous mice developed a higher frequency of hepatocellular carcinoma, lung adenocarcinoma, and B-cell lymphoma compared to wild-type mice." (PMID 39588149, 2024). "EAF2 knockout mice developed lung adenocarcinoma, hepatocellular carcinoma, B-cell lymphoma and high-grade murine prostatic intraepithelial neoplasia (mPIN)." (PMID 24260246, 2013). "EAF2 knockout mice on a 129P2/OLA-C57BL/6J background developed late-onset lung adenocarcinoma, hepatocellular carcinoma, B-cell lymphoma and high-grade prostatic intraepithelial neoplasia." (PMID 24260246, 2013).
hepatocellular carcinoma (4 papers, 2010 to 2024). A malignant tumor that arises from hepatocytes. "The association between EAF2 and hepatocellular carcinoma can be explained by the fact that EAF2 deficiency increases the risk of hepatic vascular lesions, which subsequently leads to hepatocyte loss, hepatic fibrosis, and eventually hepatocellular carcinoma via the pVHL pathway in mice." (PMID 39588149, 2024). "Consistent with its potential tumor suppressive role in the human, Eaf2/U19-knockout mice develop lung adenocarcinoma, hepatocellular carcinoma, B-cell lymphoma, and high-grade prostate intraepithelial neoplasia." (PMID 20161747, 2010).
glioblastoma (3 papers, 2016 to 2022). The most malignant astrocytic tumor (WHO grade IV). "Another novel finding in this study is that EAF2 is dramatically downregulated in glioblastoma specimens, as compared to normal brain tissue." (PMID 27259264, 2016). "In addition, EAF2 was significantly downregulated in 72 (69%) glioblastoma samples as compared to 3 (25%) normal brain tissue samples (P < 0.01)." (PMID 27259264, 2016).
Prostatic Intraepithelial Neoplasia (3 papers, 2013 to 2024). "In the current study, EAF2-deficiency in mice induced an increased incidence in prostatic intraepithelial neoplasia in a panel of murine strains." (PMID 24260246, 2013). "EAF2 and VHL double deficiency (EAF2−/−VHL+/−) mice exhibited increased vascular density compared to the control groups (wild-type, EAF2−/− and VHL+/−mice), thus resulting in a higher incidence of prostatic intraepithelial neoplasia and stromal inflammation." (PMID 39588149, 2024).
Arthritis (2 papers, 2016 to 2024). Inflammation of a joint. "However, over the long term, impaired apoptosis of GC B cells in aged EAF2−/− mice leads to an abnormal accumulation of various autoantibodies in the absence of external stimuli, making EAF2−/− mice more susceptible to collagen-induced arthritis." (PMID 39588149, 2024). "After immunization with type II collagen, mice lacking EAF2 produce high levels of collagen-specific autoantibodies and rapidly develop severe arthritis." (PMID 26935903, 2016). "Collectively, these findings suggest that CII-specific self-reactive GC B cells may not be efficiently eliminated in the absence of EAF2, allowing them to differentiate into plasma cells and produce different classes of CII-specific Ab that contribute to the pathogenesis of arthritis." (PMID 26935903, 2016).
prostate tumors (2 papers, 2011 to 2013). "In the current study, EAF2 loss was associated with increased incidence in mPIN lesions and increased vascularity in 3 murine strains and EAF2 down-regulation was associated with increased vascularity in human prostate tumors specimens." (PMID 24260246, 2013). "The expression of U19/EAF2 in xenograft prostate tumours markedly induced apoptosis and inhibited tumour growth in vivo." (PMID 21266046, 2011). "Future studies will focus on elucidating the relationship between EAF2, ADAMTS1 and the stromal microenvironment in prostate tumor development and progression." (PMID 24260246, 2013).
Autoimmunity (1 paper, 2016). The occurrence of an immune reaction against the organism's own cells or tissues. "Here the authors show that EAF2 is required for apoptosis of germinal centre B cells, and that EAF2-deficient mice develop excessive antibody responses and autoimmunity." (PMID 26935903, 2016). "Collectively, the present study suggests that EAF2 mediates B-cell apoptosis to eliminate self-reactive GC B cells and this mechanism is critical for the prevention of autoantibody production and autoimmunity." (PMID 26935903, 2016).
Burkitt lymphoma (1 paper, 2016). A rare form of malignant mature B-cell non-Hodgkin lymphoma. "Moreover, ectopic expression of EAF2 also induced apoptosis in a human Burkitt's lymphoma line Daudi, which again was accompanied by decreased BCL-2 protein expression and increased BBC3 transcript level." (PMID 26935903, 2016).
cardiac hypertrophy (1 paper, 2025). "It has been reported that ELL-associated factor 2 (Eaf2) knockout can not only induce tumorigenesis in multiple tissues but also exacerbate cardiac hypertrophy in a mouse model." (PMID 40861045, 2025).
colon cancer (1 paper, 2011). "Yet, our functional assessment using siRNA showed that silencing of EAF2 was not only capable of modulating response to lovastatin but also to simvastatin in HCT-116 colon cancer cell line under the experimental conditions applied." (PMID 21483694, 2011). "Our results indicated genes involved in the cellular response to these statins and siRNA studies confirmed the role of the EAF2 in response to these drugs in HCT-116 colon cancer cells." (PMID 21483694, 2011). "Functional validation using RNAi confirmed that silencing of EAF2 expression modulated the response of HCT-116 colon cancer cells to both statins." (PMID 21483694, 2011). "Interestingly, our results clearly show that silencing of EAF2 decreases the GI50 values of HCT-116 colon cancer cells to not only lovastatin, but also simvastatin." (PMID 21483694, 2011).
colorectal cancer (1 paper, 2024). A primary or metastatic malignant neoplasm that affects the colon or rectum. "In 2019, a single-strand conformation polymorphism assay identified intratumor heterogeneity of EAF2 frameshift mutations in colorectal cancer (CRC) and the inactivation of EAF2 in microsatellite instability-high CRC." (PMID 39588149, 2024).
fatty liver (1 paper, 2021). "In the present study, the EAf2 fraction ameliorated IR combined with fatty liver by enhancing the expression of GLUT2 and PPARα, thereby reducing intracellular lipid accumulation and ameliorating fatty liver." (PMID 34257694, 2021).
lung carcinoma (1 paper, 2020). "The tumor suppressor EAF2 is downregulated in tumors, such as lung cancer." (PMID 32878637, 2020).